RN7SKP205 (RN7SK pseudogene 205)
Gene: Miscellaneous RNA gene on chromosome 14 (23,791,930 to 23,792,236, forward strand). Ensembl gene ENSG00000222931.
Homologues: Orthologues: chimpanzee 7SK (54% identical). Paralogues in human: RN7SKP79 (67% identical), RN7SKP230 (66% identical), RN7SKP133 (65% identical), RN7SKP180 (65% identical), RN7SKP71 (65% identical), RN7SKP189 (64% identical), RN7SKP173 (64% identical), RN7SKP8 (64% identical), RN7SKP103 (64% identical), RN7SKP149 (64% identical), RN7SKP198 (64% identical), RN7SKP77 (64% identical), and 284 more.